MOG (myelin oligodendrocyte glycoprotein)
Diseases named in the same sentence as MOG in open-access papers (continued):
Sharing a sentence is not in itself a finding about the gene and the disease.
psychosis (6 papers, 2015 to 2025). "Autoimmune psychosis was suspected in three patients (4%; one with Hashimoto encephalopathy, one with anti-MOG antibody-associated psychosis, and one with mixed connective tissue disease with probable brain involvement)." (PMID 32937787, 2020). "Autoantibodies against MOG have been identified in some patients with psychosis and other psychiatric manifestations." (PMID 40757033, 2025). "Consequently, our study does not indicate that MOG antibodies play a causative role in psychosis in a subgroup of psychiatric patients." (PMID 40757033, 2025). "Another patient with atypical psychosis, as well as EEG and cMRI alterations, was tested positive for anti-MOG antibodies." (PMID 32937787, 2020). "Based on currently available data, including those in this study, routine screening for MOG-IgG in patients with isolated psychosis is clearly not indicated." (PMID 40757033, 2025).
schizophrenia (6 papers, 2011 to 2024). A major psychotic disorder characterized by abnormalities in the perception or expression of reality. "One might expect that, in patients with schizophrenia, a decreased expression of a large number of maturation marker genes might reflect the loss of cells expressing those genes (i.e., PV in FS neurons and MOG in oligodendrocytes)." (PMID 24886351, 2014). "Microarray studies of schizophrenia and bipolar disorder have frequently implicated myelin-related genes including MBP, and MOG." (PMID 22675524, 2012). "There are consistent reports of reduced expression of genes (MAG, MAL, MBP, PLP, MOG, NRG1, and Olig2, among others) associated with oligodendrocytes and myelin, and therefore involved in neuronal development or signal transmission in schizophrenia." (PMID 35326310, 2022). "RT-PCR confirmed reductions of MBP, ACTB and TB10, but not MOG or SCG10, in schizophrenia." (PMID 22675524, 2012).
tuberculosis (6 papers, 2023 to 2025). A chronic, recurrent infection caused by the bacterium Mycobacterium tuberculosis. "Differential diagnoses included infective causes (viral, mycoplasma, Lyme disease, and tuberculosis {TB}) and inflammatory etiologies (NMOSD, including AQP4 and MOG antibody-related neuroinflammation)." (PMID 41393590, 2025).
Atrophy (5 papers, 2019 to 2025). Any weakening or degeneration, especially through lack of use. "We hypothesized that MOG-ON may result in more retinal nerve fiber bundle defects than MS-ON resulting in atrophy predominantly localized in the distribution of the nerve fiber bundles." (PMID 32785840, 2021). "Cerebral MRI of the ADEM patients with mRS 4 revealed diffused cortical atrophy, which suggested severe damage in the developing brain of an ADEM with MOG-abs patient." (PMID 33329345, 2020). "Complete resolution of abnormalities in MRI findings, without atrophy, occurred in 16 patients (62%) with MOG-Ab disease and 7 patients (17%) with AQP4-Ab disease (P < .001)." (PMID 31596489, 2019).
glioma (5 papers, 2017 to 2025). A benign or malignant brain and spinal cord tumor that arises from glial cells (astrocytes, oligodendrocytes, ependymal cells). "Meanwhile, the expressions of myelin-associated proteins (MBP, MOG, MAG and CNP) were unanimously reduced in gliomas." (PMID 30034322, 2018). "Employing MRK-A, we generated cellular 2-HG IC50 values for both glioma MOG-R132H and BT142 lines as well as the HT1080 R132C human fibrosarcoma line." (PMID 29062039, 2017). "The MO marker GALC/O1 and myelin components (e.g., MBP, MOG) were under-expressed in PM gliomas." (PMID 37055795, 2023). "Using lentiviral transduction, we induced exogenous mutant IDH1 R132H protein expression in the wildtype IDH1 glioma cell line, MOG-G-UVW (MOG-R132H)." (PMID 29062039, 2017). "In IDH-mutant/PM gliomas, coordinated hypermethylation in the transcription start site (TSS)/CpG island regions was observed in MO marker (GALC/O1), myelin components (MAG, MBP, MOBP, MOG), and essential regulators of the myelination program (MYRF/C11orf9 and SOX10)." (PMID 37055795, 2023).
leukocytosis (5 papers, 2020 to 2023). "Isolated leukocytosis in the blood was more common in ADEM children with MOG antibodies (P < 0.001)." (PMID 37274199, 2023). "It is suggested that MOG antibody screening for pediatric patients with prolonged fever, lethargy, and leukocytosis in CSF and without sufficient etiological evidence for intracranial infection is needed to avoid missed diagnoses of MOG-AD." (PMID 37153594, 2023). "Given the fact that MOG-EM attacks (in common with NMOSD attacks) are often preceded by infections which may result in fever or blood leukocytosis, this might well lead to the false suspicion of infectious disease in some cases." (PMID 32883348, 2020).
leukodystrophy (5 papers, 2018 to 2023). Leukodystrophies are a group of rare, progressive, metabolic, genetic diseases that affect the brain, spinal cord and often the peripheral nerves. "We recommend to test MOG-ab in subacute and chronic progressive dementia with leukodystrophy-like MRI lesions." (PMID 34691028, 2021). "In our study, we observed leukodystrophy-like MRI pattern in two adults with MOG-ab." (PMID 34691028, 2021). "Combined with this study and previous literature, we suggest that in patient with MOG-ab, adult onset, chronically progressive disease course, delay of immunotherapy, and leukodystrophy-like abnormalities with brain atrophy on MRI were possible risk factors of bad prognosis." (PMID 34691028, 2021). "Therefore, we suggest to screen MOG-ab in patients with progressive cognitive or psychiatric symptoms and leukodystrophy-like MRI pattern to differentiate cMOG-E from untreatable diseases, which may facilitate treatment decision and prognosis." (PMID 34691028, 2021). "An ADEM-like lesion pattern on MRI is suggestive of MOG-EM/MOGAD, not NMOSD, as is a ‘leukodystrophy-like’ MRI pattern (characterized by confluent, largely symmetrical lesions), which mainly occurs in children." (PMID 37022481, 2023).
Paraparesis (5 papers, 2019 to 2023). Weakness or partial paralysis in the lower limbs. "The examination of the animal distribution according to EAE clinical scores, 30 days after MOG immunization, revealed that the beneficial effects of 11C7 come mainly from a reduction in the number of mice with paraparesis." (PMID 37558696, 2023). "For example, 30 mg/kg of PGB administered i.p. one time a day resulted in an amelioration of the disease score of MOG-induced EAE in C57BL/6 mice that reached only paraparesis." (PMID 36052340, 2022). "BFCCE with anti-MOG antibody presents characteristic clinical findings, such as paraparesis, lethargy, and memory decline, and radiological findings." (PMID 33391163, 2020).
secondary progressive MS (5 papers, 2018 to 2026). "Some evidence indicates that MOG content is strongly associated with MS, which modulates anti-myelin immune reactions in both relapsing-remitting MS (RRMS) and secondary progressive MS (SPMS) patients." (PMID 33396739, 2020).
bacterial meningitis (4 papers, 2020 to 2024). Inflammation of the membranes surrounding the brain and spinal cord due to a bacterial infection. "However, in most samples, both CSF lactate levels and absolute CSF white cell numbers were much lower in MOG-EM than in typical bacterial meningitis." (PMID 32883348, 2020). "Therefore, it could be relevant to include MOG‐IgG and AQP4‐IgG in the diagnostic workup of noncompressive myelitis secondary to bacterial meningitis." (PMID 39222058, 2024).
Brain atrophy (4 papers, 2019 to 2025). Partial or complete wasting (loss) of brain tissue that was once present. "In MS and MOG-IgG-associated disorders, reduced ALPS indices correlate with disease severity and brain atrophy." (PMID 41459546, 2025). "In summary, in addition to confirming that MOG-Abs are frequently associated with the CRION, our findings also suggest, for the first time, that brain atrophy is related to the CRION phenotype." (PMID 31736862, 2019).
chronic inflammatory demyelinating polyneuropathy (4 papers, 2022 to 2025). "It has been reported in a few cases where MOG antibodies were detected in the serum of patients with chronic inflammatory demyelinating polyneuropathy." (PMID 36601183, 2022).
diabetes (4 papers, 2017 to 2024). "These Tregitope sequences were synthesized as peptides and encoded in viral vectors (AAV) and shown to suppress inflammatory responses to co-administered antigens (Ag) (such as diabetes antigens, AAV capsid, MOG protein, OVA, and other antigens) in vitro and in vivo." (PMID 34220802, 2021). "Interestingly, a VitD analog designated Ro 26-2198 was able to reduce diabetes incidence in NOD mice enhancing the frequency and suppressive activity of Tregs in pancreatic lymph nodes, supporting therefore the likelihood that Tregs are related to MOG + PARI protective effect." (PMID 29085356, 2017).
Dystonia (4 papers, 2014 to 2024). An abnormally increased muscular tone that causes fixed abnormal postures. "In addition, complex MD featuring dystonia and abnormal eye movements has been reported in a toddler with anti-myelin oligodendrocyte glycoprotein (MOG)-associated ADEM." (PMID 34204464, 2021). "In vivo assessment of optic nerve myelination at disease end-stage showed normal density of myelinated axons and myelin thickness in optic nerve, as well as normal expression levels of CNPase, MOG and MBP in both spinal cord and cerebral cortex in animals with dystonia muscolorum." (PMID 26886550, 2016).
glioblastoma (4 papers, 2022 to 2025). The most malignant astrocytic tumor (WHO grade IV). "In cases of EGFRvIII-negative glioblastoma, central nervous system (CNS)-specific antigens (like myelin oligodendrocyte glycoprotein or MOG) can be used to prime T cells." (PMID 40308611, 2025).
Headache (4 papers, 2022 to 2026). Cephalgia, or pain sensed in various parts of the head, not confined to the area of distribution of any nerve. "Patients in the MOG-Ab (+) group frequently experienced headaches, which occurred more often than in the MOG-Ab (-) group (75.00 vs. 25.00%, χ2 = 5.419, P = 0.020)." (PMID 41676106, 2026).
measles (4 papers, 2018 to 2022). A highly contagious viral infection caused by the measles virus. "A minority among both groups had a history of vaccination prior to disease onset; more specifically, two MOG-Ab-positive children were vaccinated prior to disease onset (one received a measles vaccine, and the other received a rabies vaccine)." (PMID 36401212, 2022).
narcolepsy (4 papers, 2018 to 2026). A sleep disorder characterized by a tendency for excessive sleepiness during the day which occurs even after adequate sleep in the nighttime. "A single mutation in the hypocretin gene, which encodes hypocretin, has been explored, as has a mutation in the MOG gene, which encodes myelin oligodendrocyte glycoprotein, in a single pedigree with familial narcolepsy." (PMID 36358399, 2022). "Finally, a missense mutation in myelin oligodendrocyte glycoprotein (MOG) has been found in a rare familial form of narcolepsy, thus confirming that primary alterations in myelin may affect sleep." (PMID 31237382, 2019). "Rarer clinical manifestations of NMOSD comprise narcolepsy, acute diencephalic syndrome or muscle affection, while in MOG-EM extraneural involvement such as reversible paraspinal muscle hyperintensity have been described, as well as MOG-Abs in combined central and peripheral demyelination syndromes." (PMID 30405519, 2018).
paraneoplastic neurological syndromes (4 papers, 2023 to 2026). "Despite these limitations, our study confirms that MOG is a low-risk antibody for paraneoplastic neurological syndromes and that the clinical presentation and oncological accompaniments are extremely variable." (PMID 37360349, 2023). "Our study confirms that MOG is a low-risk antibody for paraneoplastic neurological syndromes and that the clinical presentation and oncological accompaniments are extremely variable." (PMID 37360349, 2023).
relapsing (4 papers, 2015 to 2022). "We report here on the frequency of anti-MOG B cells forming rosettes with polystyrene beads (BBR) covalently bound to the extracellular domain of rhMOG in 38 relapsing-remitting patients (RRMS) and 50 healthy individuals (HI)." (PMID 26090495, 2015). "When comparing MOG and AQP4-associated NMO spectrum disorders, it has been found that NMO patients with MOG antibodies tended to have a single attack and/or fewer attacks than NMO patients with AQP4 antibodies who experienced significantly higher rates of relapsing disease." (PMID 35399911, 2022).
rubella (4 papers, 2018 to 2022). A viral infection caused by the rubella virus. "We recently published an article about myelin oligodendrocyte glycoprotein-independent rubella infection of keratinocytes in vitro, in which first-trimester trophoblast cells were shown as rubella virus (RuV)-resistant." (PMID 35746641, 2022). "In a recently published article about myelin oligodendrocyte glycoprotein-independent rubella infection of keratinocytes in vitro, we also reported that first-trimester trophoblast cell lines showed rubella virus (RuV) resistance." (PMID 35746641, 2022).
sleep disorder (4 papers, 2023 to 2025). A change from the patient's baseline sleeping pattern, in the hours slept and/or an alteration/dysfunction in the stages of sleep. "When MOG-AD is associated with atypical manifestations such as psycho-behavioral abnormalities, sleep disorders, and frequent seizures, the presence of anti-NMDAR antibodies should be considered." (PMID 38249740, 2023). "Therefore, the presence of overlapping anti-NMDAR antibodies should be paid attention to when MOG-AD patients have manifestations such as psycho-behavioral abnormalities, sleep disorders, and frequent seizures." (PMID 38249740, 2023). "This suggested that the incidence of urinary retention was decreased and the incidence of sleep disorders, seizures, and psycho-behavioral abnormalities was increased after the coexistence of anti-NMDAR and MOG antibodies, consistent with previous findings." (PMID 38249740, 2023).
stiff-person syndrome (4 papers, 2019 to 2025). Stiff-man syndrome (SMS) is a rare neurological disorder comprising fluctuating trunk and limb stiffness, painful muscle spasms, task-specific phobia, an exaggerated startle response, and ankylosing deformities such as fixed lumbar hyperlordosis. "In some syndromes regular IVIG courses (usually 1 g/kg bodyweight every 4 to 8 weeks) can be effective (e.g. stiff-person syndrome, myelin oligodendrocyte glycoprotein (MOG) - Abs associated disease, IgLON5-syndrome)." (PMID 33324898, 2019).
uveitis (4 papers, 2023 to 2025). An inflammatory process affecting a part of or the entire uvea. "Although uveitis has been commonly associated with MS, a 2016 study showed that uveitis was present in 2/5 of atypical MS patients presenting with positive MOG-IgG; ocular manifestations have been increasingly reported in MOGAD." (PMID 41153632, 2025). "These include serum MOG IgG reported in association with uveitis, peripheral ulcerative keratitis, acute macular neuroretinopathy, serous retinal detachment, venous stasis retinopathy, pre-retinal macular haemorrhage, orbital inflammatory syndrome and orbital apex syndrome." (PMID 38783085, 2024). "Prominent retinal changes are uncommon in MOG-ON and not reported in AQP4-ON but the association between uveitis and MS is well established." (PMID 38783085, 2024).
Vertigo (4 papers, 2014 to 2025). An abnormal sensation of spinning while the body is actually stationary. "Indeed, around 74% (23/31) of the patients in our literature review showed classical demyelinating symptoms (e.g., hemihypesthesia, diplopia, hemiparesis, vertigo) alongside with MOG IgG positivity." (PMID 36384491, 2022).
asthma (3 papers, 2019 to 2024). "It needs to be mentioned that in our in vivo experiments we first activated T cells by a specific antigen (MOG peptide or HDM extract) before zinc was administered to mice during the development of EAE or the rechallenge phase within the HDM asthma model." (PMID 35121767, 2022). "We intravenously injected the same number of GFP+ MOG or OVA DNT cells into mice with OVA-induced asthma and measured the accumulation of GFP+ DNT cells in different tissues." (PMID 31534137, 2019).
atherosclerosis (3 papers, 2017 to 2023). A disease characterized by the build-up of fatty material and calcium deposition in the arterial wall resulting in partial or complete occlusion of the arterial lumen. "Apoe−/− mice fed regular chow and receiving either MOG-primed or P6-primed lymph node cells did not exhibit any aortic lesions, suggesting that an inflammatory environment created by feeding HFD is a critical factor for the atherosclerosis-promoting function of P6-specific T cells." (PMID 28280493, 2017).
brain ischemia (3 papers, 2019 to 2025). Diminished or absent blood supply to the brain caused by obstruction (thrombosis or embolism) of an artery resulting in neurologic damage. "In a study of experimental brain ischemia, microglia-like cells acted as the main antigen-presenting cells for myelin oligodendrocyte glycoprotein (MOG) antigens, leading to the expansion of previously transferred 2D2 reactive CD4+ T cells." (PMID 31001280, 2019). "The reverse transcription (RT)-qPCR results demonstrated that LIPUS treatment increased the expression levels of pro-differentiation-related genes (Olig2 and Sox10), as well as a significant up-regulation of myelin-related genes such as PLP, MBP, and MOG in mice with cerebral ischemia." (PMID 40290135, 2025). "Moreover, MOG-specific T cell proliferation with increased neurological deficits and infarction volumes has been reported at day 4 after brain ischemia in mice." (PMID 32719588, 2020).
colitis (3 papers, 2017 to 2022). Inflammation of the colon. "We found that TDC significantly inhibited the clinical symptoms of MOG-induced EAE, and additionally effectively alleviated the symptoms of colitis mice and relieved skin graft rejection." (PMID 36498875, 2022).
hepatitis B (3 papers, 2005 to 2024). "The MBP and MOG share homologies with the antigen of hepatitis B, HBsAg." (PMID 25405025, 2014).
infectious mononucleosis (3 papers, 2017 to 2024). A condition characterized by an increase in mononuclear white blood cells and swollen lymph nodes, which is usually caused by infection with the Epstein-Barr virus. "Here we present a patient who developed anti-MOG antibody-positive ADEM following infectious mononucleosis (IM) due to primary Epstein–Barr virus (EBV) infection." (PMID 28420330, 2017). "We present a patient who developed anti-MOG antibody-positive ADEM following infectious mononucleosis (IM) due to Epstein–Barr virus (EBV) infection." (PMID 28420330, 2017). "Anti-MOG antibodies have been detected in 20% of the patients with infectious mononucleosis, with no neurological manifestations due to primary EBV infection." (PMID 39845958, 2024). "None of these patients suffering infectious mononucleosis and MOG-IgG developed any clinical sign associated with MOGAD, so, MOG-IgG observed may be part from a broad non-specific autoimmune reaction associated with infection." (PMID 39845958, 2024).